NLRP5 (NLR family pyrin domain containing 5)
Description:
Component of the subcortical maternal complex (SCMC), a multiprotein complex that plays a key role in early embryonic development. The SCMC complex is a structural constituent of cytoplasmic lattices, which consist in fibrous structures found in the cytoplasm of oocytes and preimplantation embryos. They are required to store maternal proteins critical for embryonic development, such as proteins that control epigenetic reprogramming of the preimplantation embryo, and prevent their degradation or activation. Required for the localization of cortical granules to the cortex of oocytes, via association with the cortical actin scaffold. Required for cortical actin clearance prior to oocyte exocytosis and prevention of polyspermy. Involved in regulating post-fertilization Ca(2+) release and endoplasmic reticulum storage (ER) storage via regulation of cellular localization. May be involved in the localization of mitochondria to the cytoplasm and perinuclear region in oocytes and early stage embryos, independent of its role in CPL formation.
Synonyms: MATER; NALP5; PYPAF8; PAN11; CLR19.8; OZEMA19
Tractability: No criterion of Open Targets' tractability assessment is met for any kind of drug.
Gene: Protein-coding gene on chromosome 19 (55,986,775 to 56,061,810, forward strand). Ensembl gene ENSG00000171487.
Subcellular location: Cytoplasm; Cytoplasmic vesicle, secretory vesicle, Cortical granule; Mitochondrion; Nucleus, nucleolus; Golgi apparatus
Subcellular location (Human Protein Atlas): Golgi apparatus; Vesicles
Gene Ontology:
Molecular function: protein binding; tubulin binding; structural constituent of cytoplasmic lattice
Biological process: actin filament organization; cortical granule exocytosis; establishment of organelle localization; establishment of spindle localization; exocytosis; positive regulation of embryonic development; protein storage; regulation of cell division; regulation of inflammatory response; regulation of protein localization
Cellular component: cortical granule; cytoplasm; cytoplasmic lattice; Golgi apparatus; mitochondrion; nucleus; subcortical maternal complex; cell cortex; cytosol; nucleolus
Genetic constraint (gnomAD): Loss-of-function variants: 89 observed, 110.18 expected, observed/expected ratio (o/e) 0.81, 90% interval 0.68 to 0.96. The synonymous counts are far from expectation, so gnomAD's model fits this gene poorly and the ratio says little. Missense variants: 1,778 observed, 1,547 expected, observed/expected ratio (o/e) 1.15, 90% interval 1.11 to 1.2. Synonymous variants: 743 observed, 617.46 expected, observed/expected ratio (o/e) 1.2, 90% interval 1.13 to 1.28.
Homologues: Orthologues: chimpanzee NLRP5 (89% identical), macaque NLRP5 (87% identical), dog NLRP5 (62% identical), rabbit NLRP5 (59% identical), rat Nlrp5 (48% identical), mouse Nlrp5 (46% identical). Paralogues in human: NLRP14 (35% identical), NLRP13 (27% identical), NLRP8 (25% identical), NLRP7 (22% identical), NLRP2 (21% identical), NLRP12 (21% identical), NLRP3 (19% identical), NLRP11 (19% identical), NLRP4 (18% identical), NLRP1 (18% identical), NLRP9 (18% identical), NLRC3 (16% identical), and 8 more.
Diseases named in the same sentence as NLRP5 in open-access papers:
NLRP5 is named in the same sentence as 31 diseases in open-access papers, as found by Europe PMC text mining. Sharing a sentence is not in itself a finding about the gene and the disease. The quoted sentences say what the papers report.
Infertility (12 papers, 2010 to 2025). "In summary, we have identified novel biallelic mutations in TLE6 and NLRP5 in infertile female patients with EDA." (PMID 40225929, 2024). "In this study, we identify four novel compound heterozygous mutations in TLE6 and NLRP5, in two infertile female patients experiencing recurrent EDA, using whole-exome sequencing." (PMID 40225929, 2024). "In this study, we successfully identified four novel mutations in TLE6 and NLRP5 in infertile female patients diagnosed with EDA, both of which encode the SCMC complex." (PMID 40225929, 2024). "Previous studies have reported that mothers with NLRP5 mutations had offspring with characteristic clinical features and disorders, such as fertility impairment, infertility, idiopathic developmental delay and autism." (PMID 32216802, 2020). "Knock-out of the Nlrp5 gene in female mice would stagnate the early embryonic development at the two-cell stage, thereby causing infertility." (PMID 32731337, 2020). "As well as offspring with MLID, though without consistent clinical presentation or consistent epimutations, some mothers with NLRP5 variants also have periods of infertility, and reproductive outcomes including miscarriage and reported molar pregnancy." (PMID 26323243, 2015). "Offspring of mothers with NLRP5 mutations have heterogenous clinical and epigenetic features, but cases include a discordant monozygotic twin pair, individuals with idiopathic developmental delay and autism, and families affected by infertility and reproductive wastage." (PMID 26323243, 2015). "In mice, knocking out NLRP5 leads to infertility due to arrest of preimplantation embryos, highlighting its importance in reproduction." (PMID 40149478, 2025). "The NLR family has also been associated with incidents of early embryonic arrest (2- to 7-cell stage), resulting from infertile patients expressing NLRP2 and NLRP5 mutations which are illustrated as novel mutant genes." (PMID 34361119, 2021). "Furthermore, knockout of the NLRP5 and KHDC3L in female mice results in fertility defects, and human genetic mutations in these genes of the SCMC have been linked to infertility and molar pregnancies." (PMID 32410729, 2020). "Similarly, women carrying a MEG mutation (e.g., NLRP5, NLRP7, and PADI6) experience a range of reproductive outcomes, including hydatidiform moles, periods of infertility, reproductive loss, offspring with multi-locus imprinting disorders, and unaffected children." (PMID 32516339, 2020).
hypoparathyroidism (9 papers, 2013 to 2025). Hypoparathyroidism is an endocrine disorder in which the parathyroid glands in the neck do not produce enough parathyroid hormone (PTH). "More recently, the NACHT leucine-rich repeat protein NALP5 (also known as NLRP5) has been identified as a putative parathyroid autoantigen to be evaluated in patients with hypoparathyroidism." (PMID 37189745, 2023). "In addition, autoantibodies against the calcium-sensing receptor (CaSR) were detected in almost 40% of Finnish APECED patients, although this study questioned the specificity and sensitivity of anti-NLRP5 and CaSR antibodies as markers of hypoparathyroidism." (PMID 31548517, 2017). "For instance, in APS-1 with hypoparathyroidism, NLR family pyrin domain containing 5 (NLRP5) and calcium-sensing receptor (CaSR) have been identified as parathyroid autoantigens." (PMID 30002654, 2018). "Autoantibodies against NLRP5 have been detected in almost 50% of APS-1 patients with hypoparathyroidism but were absent in all APS-1 patients without hypoparathyroidism." (PMID 30002654, 2018). "NLRP5-specific autoantibodies were detected in almost half of APECED patients with hypoparathyroidism but were absent in all APECED patients without hypoparathyroidism." (PMID 31548517, 2017). "For instance, autoantibodies to the adrenal glands were identified in APS‐1 patients and autoantibodies to NLRP5 were detected in almost 50% of APS‐1 patients with hypoparathyroidism and absent in patients without hypoparathyroidism." (PMID 32994995, 2020).
female infertility (6 papers, 2005 to 2022). Diminished or absent ability of a female to achieve conception. "Collectively, these results indicate that biallelic mutations in OOEP and NLRP5 may be a potential genetic cause of female infertility." (PMID 35946397, 2022). "Several studies have demonstrated that mutations in SCMC‐related genes (TLE6, PADI6, NLRP2, NLRP5, and KHDC3L) cause human female infertility in the form of an exhibition of EEA and fragmentation." (PMID 35946397, 2022). "For example, the knock-out of mouse Nlrp5 induced female infertility due to a blockage of early embryonic development; and the injection of siRNA against Nlrp14 into fertilized eggs resulted in arrested development of embryos between 1-cell and 8-cell stages." (PMID 19682372, 2009). "Additionally, a lack of NLRP5 in mouse oocytes resulted in premature activation of the mitochondrial pool, which results in mitochondrial damage that cannot be recovered by BCL2 associated X (Bax) inactivation, and NLRP5 knockout in mice led to female infertility." (PMID 32326631, 2020).
hydatidiform mole (4 papers, 2019 to 2025). A gestational trophoblastic disorder characterized by marked enlargement of the chorionic villi, hyperplasia of the villous trophoblastic cells and hydropic changes. "Whereas, hydatidiform moles show extreme hypomethylation of maternal imprinting marks only, NLRP5 variants cause mosaic hypomethylation affecting both maternal and paternal marks, suggesting that NLRP7 may exert its effect in the oocyte, while NLRP5′s action may be postzygotic." (PMID 31466347, 2019). "Pathological variants of zinc finger protein genes such as ZFP57 and ZNF445 and of genes related to the subcortical maternal complex such as NLRP2, NLRP5, NLRP7, and KHDC3L have been identified in cases of multilocus imprinting disturbances (MLIDs) and recurrent hydatidiform moles (RHMs)." (PMID 35581658, 2022).
autoimmune oophoritis (3 papers, 2010 to 2013). Autoimmune oophoritis is a rare cause of primary ovarian insufficiency (POI). "Nlrp5 was isolated from a mouse model of autoimmune oophoritis (also termed premature ovarian failure) generated by neonatal thymectomy." (PMID 23970884, 2013). "MATER (gene name, NLRP5) was originally identified as an antigen that is involved in a mouse autoimmune oophoritis." (PMID 20830304, 2010).
Autoimmunity (3 papers, 2012 to 2021). The occurrence of an immune reaction against the organism's own cells or tissues. "The activation of the inflammasome has been proposed as a mechanism of autoimmunity in MS patients, a hypothesis that is supported by rare variants in inflammasome components NLRP1, NLRP3, NLRP5 and NLRP9 which were identified in MS families, or found to correlate with disease course and severity." (PMID 31170158, 2019).
colon cancer (1 paper, 2018). "Most intriguingly, expression of development-related NLRP5 was undetectable in normal gut-related tissues but was up-regulated in malignant gut tissue and colon cancer cell lines." (PMID 29928061, 2018). "Most interesting was the finding that the enigmatic development-related NLRP5 (also known as MATER) was not expressed in normal colon tissue but in colon cancer tissue and cell lines." (PMID 29928061, 2018).
liver cancer (1 paper, 2025). An epithelial or non-epithelial malignant neoplasm that arises from the liver. "To further investigate the in vivo function of NLRP5, we acquired mice with spontaneous liver cancer expressing Alb-Cre+/MYC+, as detailed in the Methods section." (PMID 41050084, 2025). "In vivo, specific siRNA-mediated suppression of NLRP5 in Myc-driven spontaneous liver cancer mice led to a significant reduction in tumor volume, unequivocally confirming its potent oncogenic function." (PMID 41050084, 2025). "To achieve this, we utilized siRNA transfection to knock down NLRP4 and NLRP5 in the liver cancer cell lines HCCLM3 and HepG2, and subsequently confirmed the knockdown efficiency through RT-qPCR analysis." (PMID 41050084, 2025).
lymphoma (1 paper, 2015). A malignant (clonal) proliferation of B- lymphocytes or T- lymphocytes which involves the lymph nodes, bone marrow and/or extranodal sites. "Several of the recurrently mutated genes have not previously been implicated in human lymphoma, including NLRP5, NLRP14, and GRIFIN." (PMID 26377837, 2015).
ovarian insufficiency (1 paper, 2020). "The detection of anti-NLRP5 antibodies in a small subset of patients with non-APS1 ovarian insufficiency in a previous study further underlines the importance of evaluating the prevalence of anti-KHDC3L antibodies in women with POI." (PMID 32410729, 2020). "However, anti-NLRP5 antibodies lack sensitivity for ovarian insufficiency." (PMID 32410729, 2020). "Interestingly, previous work established NLRP5 as a parathyroid-specific antigen in APS1, with potential for additional correlation with ovarian insufficiency." (PMID 32410729, 2020).
toxoplasmosis (1 paper, 2020). A parasitic disease contracted by the ingestion or fetal transmission of toxoplasma gondii. "In addition, Toxoplasmosis can significantly affect the expression of Nlrp5 and Insc leading to negative outcomes in the host." (PMID 32731337, 2020).
tumor (2 papers, 2021 to 2025). "NLRP5 knockdown suppressed HCC cell proliferation, migration, and invasion in vitro and reduced tumor growth in vivo." (PMID 41050084, 2025). "The pro-tumorigenic role of NLRP5 in HCC contrasts sharply with NLRP3, which is generally considered tumor-suppressive through its inflammasome-activating properties." (PMID 41050084, 2025). "Second, we did not explore the potential synergistic anti-tumor effects of combining NLRP5 inhibition with established HCC therapies like sorafenib." (PMID 41050084, 2025). "Despite these compelling findings, our study has certain limitations: First, we did not comprehensively evaluate NLRP5’s impact on tumor-infiltrating immune cells, such as macrophages and CD8+ T cells, which are crucial components of the tumor microenvironment." (PMID 41050084, 2025).
cancer (1 paper, 2025). A tumor composed of atypical neoplastic, often pleomorphic cells that invade other tissues. "This work significantly advances our understanding of the intricate roles of NLR family members in cancer, particularly NLRP5." (PMID 41050084, 2025).
NLRP5 also shares sentences with these, for which no sentence is quoted: APECED syndrome (2 papers); autism (2); Adrenal insufficiency (1); autoimmune hypoparathyroidism (1); breast carcinoma (1); candidiasis (1); endometritis (1); fertility disorder (1); gestational trophoblastic diseases (1); hepatocellular carcinoma (1); hyperphosphatemia (1); Hypocalcemia (1); intestinal cancer (1); Miscarriage (1); Obesity (1); ovarian tumors (1); polycystic ovarian syndrome (1); squamous cell carcinoma (1).